TRDMT1 (tRNA aspartic acid methyltransferase 1)
Description:
Specifically methylates cytosine 38 in the anticodon loop of tRNA(Asp). Has higher activity on tRNA(Asp) modified with queuosine at position 34.
Synonyms: Dnmt2; RNMT1; DMNT2; MHSAIIP; PUMET
Tractability: Small molecule: a structure with a bound ligand is known. PROTAC: ubiquitination databases record sites on it; a small molecule that binds it is known.
Target class: Enzyme; Transferase
Gene: Protein-coding gene on chromosome 10 (17,137,336 to 17,202,054, reverse strand). Ensembl gene ENSG00000107614.
Subcellular location: Cytoplasm
Pathways (Reactome):
Metabolism of RNA: tRNA modification in the nucleus and cytosol
Gene Ontology:
Molecular function: tRNA (cytidine-5-)-methyltransferase activity; tRNA methyltransferase activity; methyltransferase activity
Biological process: tRNA methylation; tRNA modification; tRNA processing; tRNA stabilization
Cellular component: cytoplasm; nucleoplasm
Genetic constraint (gnomAD): Loss-of-function variants: 30 observed, 28.32 expected, observed/expected ratio (o/e) 1.06, 90% interval 0.79 to 1.44. The upper end of that interval is the gene's LOEUF score, 1.44, which puts it in group 5 of 6, group 1 being the genes least tolerant of losing a copy. Missense variants: 408 observed, 351.34 expected, observed/expected ratio (o/e) 1.16, 90% interval 1.07 to 1.26. Synonymous variants: 144 observed, 130.8 expected, observed/expected ratio (o/e) 1.1, 90% interval 0.96 to 1.26.
Homologues: Orthologues: chimpanzee TRDMT1 (99% identical), macaque TRDMT1 (96% identical), guinea pig TRDMT1 (87% identical), dog TRDMT1 (87% identical), pig TRDMT1 (87% identical), rabbit TRDMT1 (86% identical), mouse Trdmt1 (81% identical), rat Trdmt1 (77% identical), tropical clawed frog trdmt1 (62% identical), zebrafish trdmt1 (59% identical), Drosophila melanogaster Mt2 (34% identical). Paralogues in human: DNMT1 (26% identical).
Diseases named in the same sentence as TRDMT1 in open-access papers:
TRDMT1 is named in the same sentence as 70 diseases in open-access papers, as found by Europe PMC text mining. Sharing a sentence is not in itself a finding about the gene and the disease. The quoted sentences say what the papers report.
breast carcinoma (10 papers, 2019 to 2026). "We classified breast cancer patients from the TCGA database into TRDMT1-low and -high groups using the median value of TRDMT1 transcripts per million (TPM) as the cutoff value." (PMID 32503981, 2020). "BRCA1 depletion in the HR-proficient breast cancer cell line HS578T significantly increased TRDMT1i sensitivity, showing that TRDMT1 indeed has a BRCA1-independent function that is critical for the survival of BRCA1-deficient cells." (PMID 37777505, 2023). "Knockdown of the senescent breast cancer cell 5‐methylcytosine writers “DNMT2” and “TRDMT1” resulted in a prolonged G2/M phase in the cell cycle." (PMID 36464884, 2023). "Our research re-evaluates the carcinogenic risks of plastic stabilizers and suggests that PSs may enhance breast cancer progression via targets such as MAPK14, PIM1, and TRDMT1." (PMID 41790613, 2026). "In breast cancer, 17 genes, including RNF8, DYRK2, RB1, and TRDMT1, could be used as prognostic biomarkers of breast cancer, indicating that these genes, including RNF8, might have a strong relationship with breast cancer." (PMID 31709182, 2019). "Indeed, we observed enhanced sensitivities of cells treated with siTRDMT1 to cisplatin in multiple cell lines including U2OS, breast cancer cell line MCF-7 and ovarian cancer cell line SKOV3, confirming that downregulation of TRDMT1 increases the sensitivity of tumor cells to Cisplatin." (PMID 33778494, 2021).
viral infection (8 papers, 2017 to 2022). "Here, we summarize the latest findings concerning the roles of m5C RNA methyltransferases, namely, NOL1/NOP2/SUN domain (NSUN) proteins and DNA methyltransferase 2/tRNA methyltransferase 1 (DNMT2/TRDMT1) during viral infections." (PMID 33142933, 2020). "The role of TRDMT1 in stress granules could represent a primitive cellular defense mechanism against viral infection." (PMID 34100772, 2021). "Changes in the expression levels of TRDMT1 (also called DNMT2), another m5C writer, by viral infection yielded contradictory results: upregulation in one study and downregulation in another." (PMID 34502037, 2021). "The biological function of human DNMT2/TRDMT1 is not fully recognized, however its role has been proposed during viral infection, RNA processing and stress-mediated modulation of cell proliferation and RNA protection." (PMID 34139673, 2021).
leukemia (6 papers, 2018 to 2024). A malignant (clonal) hematologic disorder, involving hematopoietic stem cells and characterized by the presence of primitive or atypical myeloid or lymphoid cells in the bone marrow and the blood. "In the present study, Trdmt1 was up-regulated and miR-181a was down-regulated significantly during human leukemia HL-60 cell differentiation after TAT-CT3 fusion protein treatment." (PMID 33331537, 2020). "Herein, we confirmed that Trdmt1-coded protein has an effect on HL-60 cells differentiation as well, suggesting that Trdmt1 might have a role of pro-differentiation in some leukemia cells." (PMID 33331537, 2020).
cardiac hypertrophy (5 papers, 2016 to 2023). "Deficiency of the tRNA methyltransferase Dnmt2/Trdmt1 in mice led to augmented dissociation of the negatively regulating Rn7sk ncRNA component, thus activating the P-TEFb complex and resulting in cardiac hypertrophy." (PMID 37612540, 2023).
glioblastoma (5 papers, 2021 to 2025). The most malignant astrocytic tumor (WHO grade IV). "Reduced representation bisulfite sequencing (RRBS) revealed significant differences in methylation-relevant DMS-linked genes in TRDMT1 KO glioblastoma cells." (PMID 37169948, 2023). "We postulate that the levels and mutation status of TRDMT1 should be considered as a prognostic marker and carefully monitored during glioblastoma progression." (PMID 37169948, 2023). "The loss of DNMT2/TRDMT1 gene affected drug-induced senescence program in glioblastoma cells that was accompanied by apoptosis resistance, DNA damage and impaired DDR and autophagic response." (PMID 34139673, 2021). "More recently, we have shown that TRDMT1 KO may modulate chemotherapy-associated responses that affected genetic stability and promoted cellular heterogeneity in stress-induced senescent glioblastoma cells." (PMID 37169948, 2023). "In the present study, the effect of CRISPR-based TRDMT1 KO on DNA methylation at a genome-wide scale at single-nucleotide resolution was analyzed using a cellular model of glioblastoma in vitro, namely U-251 MG cell line." (PMID 37169948, 2023). "In the present study, four genetically distinct cellular cancer models (breast and cervical cancer, osteosarcoma and glioblastoma cells) were utilized to investigate the impact of DNMT2/TRDMT1 gene knockout on doxorubicin (DOX)-induced ER stress and the UPR." (PMID 36273376, 2023). "TRDMT1 KO also affected microRNA pools during doxorubicin-stimulated ER stress in glioblastoma cells." (PMID 37169948, 2023). "Reduced representation bisulfite sequencing (RRBS) was considered to comprehensively evaluate DNA methylome in glioblastoma cells with TRDMT1 KO." (PMID 37169948, 2023). "CRISPR-based approach was used to obtain TRDMT1 KO glioblastoma cells." (PMID 37169948, 2023). "In the present study, we have used four different cancer cell types (breast and cervical cancer, osteosarcoma and glioblastoma cells) to analyze the effects of DNMT2/TRDMT1 gene knockout during doxorubicin- and etoposide-induced senescence and the impact of AZA post-treatment." (PMID 34139673, 2021). "Despite the fact that glioblastoma, a common and malignant brain tumor, is widely characterized in terms of genetic and epigenetic markers, there are no data on TRDMT1-related changes in 5-methylcytosine pools in the genome." (PMID 37169948, 2023). "In the present study, DNMT2/TRDMT1 gene knockout-mediated effects were investigated during doxorubicin (DOX)-induced ER stress and PERK-, IRE1- and ATF6-orchestrated UPR in four genetically different cellular models of cancer (breast and cervical cancer, osteosarcoma and glioblastoma cells)." (PMID 36273376, 2023). "In glioblastoma (GBM), NSUN2, DNMT3B, NSUN5, TRDMT1, ALKBH1, and HNRNPC were selected." (PMID 40565233, 2025).
osteosarcoma (5 papers, 2021 to 2025). A usually aggressive malignant bone-forming mesenchymal neoplasm, predominantly affecting adolescents and young adults. "TRDMT1 knockout (KO) increased sensitivity to PARP inhibitors in osteosarcoma cells and TRDMT1 was proposed to be a novel target in DNA damage-based anti-cancer therapies." (PMID 37169948, 2023). "It was also reported that DNMT2/TRDMT1, a writer of RNA m5C at sites of DNA damage, is required for efficient homologous recombination (HR) and provided resistance of U-2 OS osteosarcoma cells to radiotherapy and PARP inhibitors." (PMID 34139673, 2021). "Moreover, redox homeostasis, proliferation-related pathways, and DNMT2/TRDMT1-based effects could be modulated as part of an anti-osteosarcoma strategy, reflecting the diverse phenotypic features of osteosarcoma cells." (PMID 39340806, 2024).
colorectal cancer (4 papers, 2020 to 2025). A primary or metastatic malignant neoplasm that affects the colon or rectum. "The cell cycle G2/M phase is lengthened when the 5-methylcytosine writers DNMT2 and TRDMT1 are knocked down in senescent colorectal cancer cells." (PMID 37670275, 2023). "Specifically, in hepatocellular carcinoma, DNMT2 promotes tumour progression and enhances bortezomib resistance by repressing the pro‐apoptotic gene TNFSF10; in colorectal cancer, a TRDMT1‐regulated tRNA fragment tRF‐3022b modulates apoptosis and M2 macrophage polarisation." (PMID 40984038, 2025).
glioma (4 papers, 2021 to 2025). A benign or malignant brain and spinal cord tumor that arises from glial cells (astrocytes, oligodendrocytes, ependymal cells). "Knockdown of TRDMT1 gene, may affect cancer cell fate during chemotherapy for glioma." (PMID 37934565, 2023). "Interestingly, glioma-specific regulators such as NSUN5 and TRDMT1 exhibited localized enrichment in oligodendrocytes and fibroblasts, suggesting their roles in neuro-glial remodeling and stress adaptation." (PMID 40565233, 2025).
ovarian carcinoma (3 papers, 2021 to 2023). A malignant neoplasm originating from the surface ovarian epithelium. "Accordingly, a TRDMT1 G155V mutation in an ovarian cancer super responder to platinum treatment." (PMID 33778494, 2021). "Indeed, TRDMT1 G155V mutation identified in a patient with ovarian cancer is sensitive to platinum therapy." (PMID 33778494, 2021). "In contrast, high expression of TRDMT1 in patients with ovarian cancer correlates with platinum resistance." (PMID 33778494, 2021). "In this study, we explored the relevance of TRDMT1 in the treatment response of ovarian cancers." (PMID 33778494, 2021).
Skin cutaneous melanoma (3 papers, 2022 to 2023). "We also found that RARA-AS1 was significantly correlated with all methyltransferase genes (DNMT3B, DNMT3A, TRDMT1, and DNMT) in KIRC, LGG, Skin cutaneous melanoma (SKCM), and UVM." (PMID 37833349, 2023).
spina bifida (3 papers, 2018 to 2023). A congenital neural tube defect in which vertebrae are not fully formed. "DNMT2 (TRDMT1) polymorphisms have been also associated with spina bifida risk and increased folate levels in red blood cells." (PMID 30477220, 2018). "The tRNA aspartic acid methyltransferase 1 (TRDMT1) is significantly associated with spina bifida." (PMID 37612540, 2023). "As in the exome dataset of proband SB1A with the EFNB1 variant (rs772228172), four variants were annotated as homozygous (CUBN, COMT, PTCH1 and TRDMT1) and eight variants as heterozygous (CUBN,MTRR, and VANGL1) in the reported spina bifida-related genes." (PMID 35741713, 2022).
neuroblastoma (2 papers, 2020 to 2025). Neuroblastoma (NB) is the most common solid, extracranial childhood tumor. "This study reveals significant associations between TRDMT1 gene polymorphisms and neuroblastoma susceptibility, suggesting their potential value as biomarkers for genetic risk assessment." (PMID 40984038, 2025). "Our study revealed a significant association between TRDMT1 gene polymorphisms (rs7074891 T>C, rs10904887 T>C, and rs2273734 C>T) and neuroblastoma susceptibility." (PMID 40984038, 2025). "Stratification analysis for the association between TRDMT1 risk genotypes and neuroblastoma susceptibility in Jiangsu children." (PMID 40984038, 2025). "The impact of tRNA Dimethyltransferase 1 (TRDMT1), a primary methyltransferase catalysing 5‐methylcytosine (m5C) RNA modification, on neuroblastoma susceptibility remains unexplored." (PMID 40984038, 2025). "TRDMT1 polymorphisms are significantly associated with neuroblastoma susceptibility, providing insights into their genetic and epigenetic mechanisms and potential as biomarkers and therapeutic targets." (PMID 40984038, 2025). "Survival analysis confirmed that elevated TRDMT1 expression is associated with poorer prognosis in neuroblastoma patients." (PMID 40984038, 2025). "For the first time, we demonstrated that TRDMT1 SNPs are significantly associated with neuroblastoma susceptibility." (PMID 40984038, 2025). "In this study, we identified associations between TRDMT1 gene polymorphisms (rs7074891 T>C, rs10904887 T>C and rs2273734 C>T) and neuroblastoma susceptibility in a Chinese paediatric population." (PMID 40984038, 2025). "Overall, our findings identified the associations between m5C key gene TRDMT1 polymorphisms and neuroblastoma susceptibility, prognosis, and clinical characteristics." (PMID 40984038, 2025). "TRDMT1, a key m5C methyltransferase, has been implicated in cancer progression, but its role in neuroblastoma remains undefined." (PMID 40984038, 2025). "Through comprehensive analyses, including stratification analysis, combined risk genotype analysis, eQTL analysis, survival analysis and clinical correlation analysis, our findings highlight TRDMT1 as a potential marker for neuroblastoma risk assessment and a therapeutic target." (PMID 40984038, 2025). "Given its pivotal role in m5C modification and implication in tumorigenesis, investigating TRDMT1 gene polymorphisms in neuroblastoma may help elucidate its contribution to tumour susceptibility." (PMID 40984038, 2025). "These associations were further supported by stratification and combined risk genotype analyses, suggesting that TRDMT1 genetic variants may contribute to individual differences in neuroblastoma risk." (PMID 40984038, 2025). "Association of TRDMT1 gene polymorphisms with neuroblastoma risk in children from Jiangsu province." (PMID 40984038, 2025). "However, the precise role of TRDMT1 and its polymorphisms in neuroblastoma remains unexplored." (PMID 40984038, 2025). "The expression level of TRDMT1 in normal adrenal gland tissue was significantly lower than that in neuroblastoma tissue." (PMID 40984038, 2025). "Genotyping of the TRDMT1 gene was successfully conducted in 394 neuroblastoma patients and 473 control samples among the 402 neuroblastoma patients and 473 controls." (PMID 40984038, 2025). "In summary, these findings suggest that aberrantly high TRDMT1 expression may play a critical role in the development and progression of neuroblastoma." (PMID 40984038, 2025). "Likewise, TRDMT1 (DNMT2) was reported to have a higher activation in small cell lung cancer (SCLC), neuroblastoma, and medulloblastoma compared to all other cancers." (PMID 32708015, 2020).
Obesity (2 papers, 2021 to 2022). Accumulation of substantial excess body fat. "The target genes TRDMT1, ZNF418, NAT1, and CDC7 have been experimentally associated through their expression levels or through knockouts, or are used as biomarkers, for waist circumference, BMI, obesity, or insulin resistance." (PMID 33957961, 2021).
ovarian tumors (2 papers, 2021 to 2023). "Several TC-HR proteins including TRDMT1 are commonly upregulated in breast and ovarian tumors, regardless of the BRCA status, and contribute to PARPi resistance in cancer cells, suggesting TRDMT1 as a promising therapeutic target for cancer treatment." (PMID 37777505, 2023).
bladder cancer (1 paper, 2025). "In bladder cancer (BLCA), NSUN2, IGF2BP2, YTHDC1, ALKBH5, TRDMT1, and ZC3H13 were identified, with NSUN2—a 5-methylcytosine (m5C) writer—previously shown to promote tumorigenesis and cancer stemness by stabilizing CCND1 mRNA and driving epithelial–mesenchymal transition." (PMID 40565233, 2025).
Breast tumors (1 paper, 2020). "Similar to BRCA1 deficiency, low expression of TRDMT1 in breast tumors may induce genomic instability but also render tumors responsive to radiotherapy." (PMID 32503981, 2020). "Breast tumors expressing low levels of TRDMT1 are more responsive to radiotherapy, supporting the role of TRDMT1 in DSB repair." (PMID 32503981, 2020).
colorectal tumour (1 paper, 2024). "There were no obvious differences in NSUN6, NSUN7 and TRDMT1 expression between the colorectal tumour tissues and adjacent normal tissues." (PMID 38468490, 2024).
congenital heart defects (1 paper, 2021). "Furthermore, genetic variants of SHMT1, BHMT, MGST1, MGMT, MTHFS, GNMT, and TRDMT1 were associated with an increased risk of congenital heart defects after prenatal antidepressant exposure." (PMID 33981330, 2021).
lung adenocarcinoma (1 paper, 2022). A carcinoma that arises from the lung and is characterized by the presence of malignant glandular epithelial cells. "TRDMT1 and JMJD7.PLA2G4B genes were downregulated, while the other 10 genes were significantly overexpressed in lung adenocarcinomas compared with normal tissues." (PMID 35812404, 2022).
metastatic tumors (1 paper, 2023). "Regarding the expression of DNMT2/TRDMT1, a further decline in metastatic tumors compared to primary carcinomas was noted (p < 0.001)." (PMID 37894317, 2023).
premature ovarian failure (1 paper, 2021). "Here, we present the role of TRDMT1 in reactive oxygen species-induced granulosa cells death, which is considered an important cause of premature ovarian failure." (PMID 34100772, 2021).
Sepsis (1 paper, 2022). Sepsis is defined as life-threatening organ dysfunction caused by a dysregulated host response to infection. "We constructed a Trdmt1 knockout rat and adopted the LPS‐induced sepsis model." (PMID 35474613, 2022). "Then, we monitored the survival rate of Trdmt1 knockout rats in 5 mg/kg LPS‐induced sepsis model." (PMID 35474613, 2022). "Here, we applied the LPS‐induced sepsis model to analyze Trdmt1 gene function." (PMID 35474613, 2022). "Our results underscore a critical role of Trdmt1 in regulating the levels of inflammatory cytokines, especially TNF‐α in the sepsis model." (PMID 35474613, 2022).